TNIK (TRAF2 and NCK interacting kinase)
Description:
Serine/threonine kinase that acts as an essential activator of the Wnt signaling pathway. Recruited to promoters of Wnt target genes and required to activate their expression. May act by phosphorylating TCF4/TCF7L2. Appears to act upstream of the JUN N-terminal pathway. May play a role in the response to environmental stress. Part of a signaling complex composed of NEDD4, RAP2A and TNIK which regulates neuronal dendrite extension and arborization during development. More generally, it may play a role in cytoskeletal rearrangements and regulate cell spreading. Phosphorylates SMAD1 on Thr-322. Activator of the Hippo signaling pathway which plays a pivotal role in organ size control and tumor suppression by restricting proliferation and promoting apoptosis. MAP4Ks act in parallel to and are partially redundant with STK3/MST2 and STK4/MST2 in the phosphorylation and activation of LATS1/2, and establish MAP4Ks as components of the expanded Hippo pathway.
Synonyms: KIAA0551; MAP4K7; MRT54
Tractability: Small molecule: a structure with a bound ligand is known; a high-quality ligand is known; it has a high-quality binding pocket; it belongs to a druggable protein family. PROTAC: ubiquitination databases record sites on it; its protein half-life has been measured; a small molecule that binds it is known.
Target class: Kinase; STE protein kinase group; STE protein kinase STE20 family; STE protein kinase MSN subfamily; Protein Kinase; Enzyme
Gene: Protein-coding gene on chromosome 3 (171,058,414 to 171,460,408, reverse strand). Ensembl gene ENSG00000154310.
Subcellular location: Nucleus; Cytoplasm; Recycling endosome; Cytoplasm, cytoskeleton
Subcellular location (Human Protein Atlas): Nucleoplasm; Cytosol
Pathways (Reactome):
Cellular responses to stimuli: Oxidative Stress Induced Senescence
Gene Ontology:
Molecular function: protein binding; protein kinase activity; protein serine kinase activity; protein serine/threonine kinase activity; ATP binding
Biological process: actin cytoskeleton organization; cytoskeleton organization; intracellular signal transduction; positive regulation of JNK cascade; positive regulation of microvillus assembly; protein autophosphorylation; protein phosphorylation; regulation of dendrite morphogenesis; MAPK cascade; neuron projection morphogenesis; regulation of MAPK cascade; positive regulation of intracellular signal transduction; regulation of JNK cascade
Cellular component: apical plasma membrane; cytoplasm; cytoskeleton; cytosol; extracellular exosome; nucleoplasm; nucleus; glutamatergic synapse; postsynaptic density, intracellular component; presynapse; recycling endosome
Genetic constraint (gnomAD): Loss-of-function variants: 43 observed, 163.85 expected, observed/expected ratio (o/e) 0.26, 90% interval 0.2 to 0.34. The upper end of that interval is the gene's LOEUF score, 0.34, which puts it in group 1 of 6, group 1 being the genes least tolerant of losing a copy. Missense variants: 1,106 observed, 1,610.9 expected, observed/expected ratio (o/e) 0.69, 90% interval 0.65 to 0.72. Synonymous variants: 565 observed, 573 expected, observed/expected ratio (o/e) 0.99, 90% interval 0.92 to 1.06.
Gene-disease validity (ClinGen):
ClinGen rates the evidence that TNIK causes each of these diseases.
non-syndromic intellectual disability (autosomal recessive): Limited. An intellectual disability that is not part of a larger syndrome.
Homologues: Orthologues: chimpanzee TNIK (99% identical), rabbit TNIK (99% identical), dog TNIK (99% identical), guinea pig TNIK (99% identical), pig TNIK (99% identical), mouse Tnik (99% identical), rat Tnik (99% identical), macaque TNIK (96% identical), tropical clawed frog tnik (91% identical), zebrafish tnika (78% identical), Drosophila melanogaster msn (47% identical), Caenorhabditis elegans mig-15 (41% identical). Paralogues in human: MAP4K4 (68% identical), MINK1 (65% identical), NRK (36% identical), SLK (21% identical), MAP4K3 (19% identical), TAOK1 (18% identical), STK10 (18% identical), MAP4K5 (17% identical), MAP4K2 (17% identical), TAOK3 (16% identical), TAOK2 (16% identical), MAP4K1 (16% identical), and 23 more.
Diseases named in the same sentence as TNIK in open-access papers:
TNIK is named in the same sentence as 77 diseases in open-access papers, as found by Europe PMC text mining. Sharing a sentence is not in itself a finding about the gene and the disease. The quoted sentences say what the papers report.
colorectal cancer (22 papers, 2015 to 2026). A primary or metastatic malignant neoplasm that affects the colon or rectum. "Inhibition of TNIK is expected to block the aberrant Wnt/β-catenin signaling caused by colorectal cancer mutations." (PMID 36361804, 2022). "Colorectal cancers contain many mutations in the Wnt/β-catenin signaling pathway genes upstream of TNIK, such as the adenomatous polyposis coli (APC) tumor suppressor gene." (PMID 36361804, 2022). "For example, the overexpression of NUAK1 has been linked to a poor prognosis in ovarian and colorectal cancers, and the oncogenic role of TNIK is deemed important in colorectal cancer." (PMID 35267421, 2022). "TNIK regulates Wnt signalling in the most downstream part of the pathway, and its pharmacological inhibition has been expected to block the signal even in colorectal cancer cells with mutation in the APC or CTNNB1 gene." (PMID 27562646, 2016). "Results obtained with a preclinical TNIK inhibitor in human colorectal cancer cells show efficient abrogation of MYC expression and consequently impaired dimerization with its interaction partner MAX." (PMID 41785318, 2026). "TNIK has previously been identified as an essential factor for transactivating Wnt signal target genes, and its inhibition has been proven to eradicate colorectal cancer stem cells." (PMID 36408691, 2023). "In colorectal cancer, it was found that TNIK is necessary for tumor-initiating function of stem cells in the intestines, and in acute myeloid leukemia blasts TNIK reduces survival rate due to the activation of Wnt signaling." (PMID 37215541, 2023). "Two subsequent studies identified TNIK as a protein that interacts with TCF4 in colorectal cancer cells." (PMID 36361804, 2022). "Since TNIK activates the Wnt/β-catenin/T-cell factor 4 pathway and its activation contributes to the transformation of cells to cancer cells, particularly colorectal cancer, it can be applied to Wnt-activated colorectal cancer." (PMID 36230527, 2022). "TNIK is a promising therapeutic target in the treatment of colorectal cancer, which is characterized by abnormal Wnt-signaling." (PMID 36355520, 2022). "TRAF2- and NCK-interacting kinase (TNIK) has emerged as a promising therapeutic target for colorectal cancer because of its essential role in regulating the Wnt/β-catenin signaling pathway." (PMID 36361804, 2022). "TNIK inhibition has arisen as an appealing anti-cancer treatment option because of its role in Wnt-mediated colorectal carcinoma." (PMID 36355520, 2022). "We have previously identified TNIK as an essential regulatory component of Wnt signaling in colorectal cancer cells." (PMID 33400690, 2021). "We have previously identified TRAF2- and NCK-interacting protein kinase (TNIK) as an essential factor for the transactivation of Wnt signal target genes and shown that its inhibition leads to eradication of colorectal cancer stem cells." (PMID 33400690, 2021). "As is the case in colorectal cancer, here we also identified TNIK as a therapeutic target in OS, and pharmacological TNIK inhibition suppressed the growth of OS cells in vitro and in vivo." (PMID 33400690, 2021). "We found that TNIK was essential for transactivation of Wnt target genes and that colorectal cancer cells were highly sensitive to TNIK inhibition." (PMID 32429395, 2020). "TNIK-Wnt signaling is an important oncogenic pathway, and leads to the development of colorectal cancer and the maintenance and expansion of leukemia stem cells." (PMID 32242021, 2020). "We previously reported that TNIK was required for the tumor-initiating function of colorectal cancer stem cells." (PMID 32429395, 2020). "It is of interest to design and develop efficient inhibitors to the TNIK protein target in Wnt signaling pathways in the context of colorectal cancer (CRC) using molecular dockingmodels." (PMID 32831519, 2020). "Given its importance in regulating the Wnt pathway, TNIK is considered as a druggable target in colorectal cancer." (PMID 29914080, 2018).
colorectal cancer (continued). "TNIK can act as a positive regulator of the canonical Wnt signaling pathway in colorectal cancer cells." (PMID 30063210, 2018). "KY-05009 is a novel aminothiazole developed as a TNIK inhibitor that exhibits anti-cancer activity in human colorectal cancer cells." (PMID 28467797, 2017). "TRAF2- and NCK-interacting kinase (TNIK) represents one of the crucial targets for Wnt-activated colorectal cancer." (PMID 27650168, 2016). "Since the kinase activity is essential for activation of the β-catenin pathway, TNIK is an attractive therapeutic target against colorectal cancer that obtains aberrant Wnt signaling." (PMID 27650168, 2016). "Herein, we identified a novel mechanism of action for MBZ which targets an oncogenic protein, TNIK, in a clinical-relevant signaling pathway, particular in colorectal cancer." (PMID 27650168, 2016). "TNIK was essential for full activation of Wnt signalling, and colorectal cancer cells were highly dependent on TNIK for growth." (PMID 27562646, 2016). "Studies reveal that TNIK is essential for the activation of Wnt target genes, allowing for proliferation of tumor cells, which induces tumor progression of myelogenous leukemia, colorectal cancer and lung non-small cell carcinoma." (PMID 37215541, 2023). "Colorectal cancer growth is highly dependent on the kinase activity of TNIK." (PMID 36361804, 2022). "Therefore, it is of interest to design and develop efficient inhibitors to the TNIK protein targetin Wnt signaling pathways in the context of colorectal cancer (CRC) using molecular docking models." (PMID 32831519, 2020). "TNIK regulates stemness in small intestine crypts and supports colorectal cancer formation." (PMID 32242021, 2020). "Small-molecule inhibitors of TNIK have been developed to treat colorectal cancers." (PMID 29914080, 2018). "TNIK is required for the tumour-initiating function of colorectal cancer stem cells." (PMID 27562646, 2016). "In colorectal cancer, where the Wnt signaling pathway is the most prominent, NCB-0846 has been shown to bind to TNIK in an inactive structure, thereby inhibiting the activation of the Wnt pathway and blocking intestinal tumorigenesis and tumorigenic activity." (PMID 38226156, 2024). "TNIK phosphorylates S154 of TCF4, and its catalytic activity has proved to be essential for the colorectal cancer growth." (PMID 27650168, 2016). "TNIK appeared to be an essential factor for WNT signaling and stemness in colorectal cancer and might be responsible for chemoresistance in osteosarcoma." (PMID 34572869, 2021).
breast carcinoma (7 papers, 2012 to 2024). "MDA-MB-231 human breast cancer cells targeted knockout of TNIK validated that the disruption of TNIK restrained the key proteins expression of Wnt/β-catenin signalling and EMT." (PMID 35095493, 2021). "RNA interference-mediated suppression of five candidate genes (DDX10, SKA3, EPHA5, CLTC and TNIK) led to inhibition of breast cancer cell growth." (PMID 23496902, 2013). "CD40-induced NF-κB, which also involves TNIK, protects cells from apoptosis in some low-grade B-cell malignancies and promotes cell transformation of epithelial cells, for instance in breast cancer." (PMID 22904686, 2012). "Using whole genome mate pair sequencing and RNA interference assays, we have discovered a number of novel gene rearrangements in breast cancer genomes and identified DDX10, SKA3, EPHA5, CLTC and TNIK as potential cancer genes with impact on the growth and proliferation of breast cancer cells." (PMID 23496902, 2013). "Studies have shown that in the breast cancer cell line MDA-MB-231, WBP2 initiates cellular Wnt activity through the upregulation of GPS1 and TNIK." (PMID 38289496, 2024). "TNIK is required for JNK1 activation, a kinase that activates the AP-1 complex, whereas MMP13, a metalloprotease, that is regulated through the same signalling pathway, is considered as a marker of breast cancer invasiveness." (PMID 34403459, 2021).
gastric cancer (7 papers, 2015 to 2024). A primary or metastatic malignant neoplasm involving the stomach. "The proto-oncoprotein TNIK exhibits overexpression in various malignancies, including prostate cancer (PCa), multiple myeloma, pancreatic cancer, hepatocellular carcinoma, and gastric cancer." (PMID 38226156, 2024). "Amplification of the TNIK gene is detectable in 7% of gastric cancers, and TNIK is reportedly one of several putative driver oncogenes." (PMID 33400690, 2021). "Furthermore, TNIK has been shown to play a role in the PI3K-Akt signaling pathway by regulating Akt activation in gastric cancer growth." (PMID 39268461, 2024). "Recently, amplification of TNIK has been reported in 7% (8/106) of gastric cancer patients." (PMID 27562646, 2016). "For example, TNIK protein phosphorylates AKT and promotes the proliferation of gastric cancer cells." (PMID 38226156, 2024). "As a member of serine/threonine protein kinase family, TNIK has been proved to play a cancer-promoting role in CRC, gastric cancer, lung cancer, prostate cancer and other diseases." (PMID 36287174, 2022).
schizophrenia (7 papers, 2011 to 2025). A major psychotic disorder characterized by abnormalities in the perception or expression of reality. "Traf2 and Nck-interacting protein kinase (TNIK), a schizophrenia susceptibility gene, is associated with risperidone treatment response." (PMID 39268461, 2024). "Similar to Sema/Plexin signaling, TNIK is also associated with various neurological disorders, including schizophrenia and intellectual disabilities." (PMID 30063210, 2018). "Tnik (TNIK) is a kinase that localizes to the post-synaptic density and interacts with other proteins strongly associated with schizophrenia including NMDA receptors and DISC1." (PMID 21440632, 2011). "TNIK is found in postsynaptic density complexes enriched for risk genes associated with autism spectrum disorder, intellectual disability, developmental delay, and schizophrenia." (PMID 40672381, 2025). "A number of circumstantial lines of evidence imply that TNIK is involved in schizophrenia and bipolar disorder." (PMID 38292191, 2024). "Using this system we focused on three postsynaptic proteins DISC1, TNIK and PSD-93/DLG2 each of which is encoded by a schizophrenia susceptibility gene." (PMID 21440632, 2011). "Based on previous genetic studies and the significance of TNIK in the function of schizophrenia, ID, glutamate receptors, and spine morphology, we hypothesized that TNIK may participate in the pathology of TLE and may be a potential therapeutic target for epilepsy." (PMID 38292191, 2024). "Recent studies have shown that TNIK binds with NMDAR and DISC1, which play important roles in schizophrenia." (PMID 38292191, 2024).
Intellectual disability (5 papers, 2018 to 2025). "For example, rs13084442 on 3q26.31 (multivariate z = 6.34, P = 2.32 × 10−10) is an eQTL of TNIK, a gene associated with neurogenesis and intellectual disability." (PMID 36800424, 2023). "In any case, the recent identification of biallelic loss-of-function variants in TNIK in individuals with intellectual disability suggests a direct link between abrogated complex formation between TNIK and the β4b-L125P mutant and impaired cognitive function in humans." (PMID 32176688, 2020).
colon cancer (4 papers, 2021 to 2025). "TNIK is essential for colon cancer growth and tumor initiation." (PMID 40492125, 2025). "Treatment with NC-1, an oral inhibitor of TNIK, was reported to suppress the ALDH-positive colon cancer CSC population, as well as growth of tumor xenografts in preclinical models." (PMID 34344863, 2021).
idiopathic pulmonary fibrosis (4 papers, 2025 to 2026). Idiopathic pulmonary fibrosis (IPF) is a nonneoplastic pulmonary disease that is characterized by the formation of scar tissue within the lungs in the absence of any known cause. "Proof-of-concept was provided in a phase 2a trial of a de novo-designed TNIK inhibitor in idiopathic pulmonary fibrosis, in which safety, tolerability, and pharmacodynamic target engagement were demonstrated, with a trend toward reduced functional decline." (PMID 41986665, 2026). "To evaluate the impact of inhibiting TRAF2 signaling in vivo, we utilized the TNIK inhibitor (KY05009) in mice with pulmonary fibrosis induced by irradiation." (PMID 40438045, 2025). "Within 30 months, Insilico Medicine’s ISM001-055, an AI-engineered inhibitor aimed against Traf2- and Nck-interacting kinase (TNIK) for idiopathic pulmonary fibrosis, progressed from concept to phase I trials, demonstrating the efficacy of AI in pharmaceutical development." (PMID 40547482, 2025). "Thus, TNIK is an attractive target for lung fibrosis, supported by both the unique omic-driven analysis and other AI-based approaches." (PMID 38459338, 2025).
Cognitive impairment (3 papers, 2020 to 2024). Abnormal cognition is characterized by deficits in thinking, reasoning, or remembering. "While rodent models of TNIK dysfunction have abnormal spontaneous synaptic activity and cognitive impairment, the role of mutations found in patients with TNIK protein deficiency and TNIK protein kinase activity during early stages of neuronal and synapse development has not been characterized." (PMID 38638602, 2024). "We also found significant DNA methylation changes in genes outside of canonical pathways implicated in high-altitude acclimatization (i.e., HIF and RAS), including significant DNA methylation changes in genes associated with cognitive impairment [ASH1L and TNIK]." (PMID 34262470, 2021). "In addition, TNIK knockout mice have cognitive impairment and reduced adult neurogenesis." (PMID 38638602, 2024).
lung adenocarcinoma (3 papers, 2014 to 2024). A carcinoma that arises from the lung and is characterized by the presence of malignant glandular epithelial cells. "Before evaluating the effect of KY-05009 on TGF-β-mediated EMT in human lung adenocarcinoma A549 cells, we investigated the binding mode and main interactions of KY-05009 with TNIK." (PMID 25337707, 2014). "Moreover, TNIK hyperactivity contributed to human lung adenocarcinoma cell metastasis." (PMID 38226156, 2024). "Therefore, in this study, we evaluated the effect of a novel aminothiazole inhibitor of TNIK, 5-(4-methylbenzamido)-2-(phenylamino)thiazole-4-carboxamide (hereinafter referred to as our database code number, KY-05009), on TGF-β-mediated EMT in human lung adenocarcinoma A549 cells." (PMID 25337707, 2014).
lung carcinoma (3 papers, 2021 to 2025). "Given the convergence of Wnt and transforming growth factor-β (TGFβ) signalling, we examined the effects of a small-molecule TNIK inhibitor (named NCB-0846) on the TGFβ1-induced EMT of lung cancer cells." (PMID 33244122, 2021). "NCB-0846, but not NCB-0970, inhibited the expression of TNIK as well as the expression of Wnt target gene products, including Axin1, Axin2 and cMyc, in A549 lung cancer cells." (PMID 33244122, 2021).